MIR5003 (microRNA 5003)
Synonyms: hsa-mir-5003
Gene: MicroRNA gene on chromosome 5 (172,662,165 to 172,662,263, forward strand). Ensembl gene ENSG00000265160.
Homologues: Orthologues: chimpanzee MIR5003 (100% identical).